RB1 (RB transcriptional corepressor 1)
Diseases named in the same sentence as RB1 in open-access papers (continued):
Sharing a sentence is not in itself a finding about the gene and the disease.
tumor (continued). "Rbfox2 in the structure of SGs affecting the mRNA of Rb1, a tumor suppressor, and reducing its stability and expression, increases the proliferation process in cancer cells." (PMID 34604242, 2021). "We discovered a new driver of MPNSTs, an oncogenic GTPase named RABL6A, that functions in part by inhibiting the RB1 tumor suppressor." (PMID 34065204, 2021). "The pRB protein, coded by the RB1 gene, is a famed tumor suppressor in OC, which is similar to our results, and was related to acquired chemotherapy resistance and OC recurrence." (PMID 33785763, 2021). "To determine if MYCN expression synergizes with Rb1 loss to drive a molecular program associated with NEPC, we performed bulk RNA-seq on histologically distinct tumor foci ranging from adenocarcinoma to NEPC." (PMID 34099734, 2021). "The RB1 tumour suppressor is activated downstream of CDK4 and CDK618 and its deletion predicts a mechanism for resistance to CDK4/6 inhibitors." (PMID 34580349, 2021). "Descriptive genomic analysis of pre-NAC tumor samples identified mutations in ERBB2 and DNA repair genes; ATM, RB1, FANCC, and ERCC2 were associated with tumor response to NAC." (PMID 33799514, 2021). "Seven of the 64 tumour suppressors (ACVR2A, CSMD3, EPS15, MAP2K4, NF1, PBRM1 and RB1) had intronic mis-splicing mutations in multiple tissues." (PMID 33420369, 2021). "Irreversible defects in RB1 tumor suppressor functions often predict poor outcomes in cancer patients." (PMID 34359636, 2021). "Structural variation involved in complex rearrangement patterns leading to disruption of RB1 in eight tumours contributed to the majority of the total rearrangements (191 of the total 356 rearrangements detected)." (PMID 33670346, 2021). "In agreement with our proteomic data, we find reduced levels of the CS protein in each of the tumor samples (RB1-6) compared to the controls (Ret1-3)." (PMID 34404904, 2021). "Analysis of the plasma-derived cfDNA, blind to the tumour results, identified seven RB1 SNV mutations, which were subsequently confirmed in the tumour." (PMID 33805427, 2021). "This assay highlighted the heterogeneity in the expression of both GAPDH and RB1, confirming that CTCs represent a heterogeneous group of tumor cells." (PMID 33761970, 2021). "Ten tumours carried structural rearrangements involving RB1 ranging from relatively simple to extremely complex rearrangement patterns, including a chromothripsis-like pattern in one tumour." (PMID 33670346, 2021). "The tumours with RB1 alterations also exhibited aberrant expression of Rb1 and p16 by immunohistochemistry." (PMID 33737597, 2021). "Our finding of RB1 deletions in 34% of tumours with CDKN2A deletion makes responses to CDK4/CDK6 antagonists less likely and underpins our finding that the CDK4/CDK6 inhibitor Palbociclib had marginal effects on primary cell survival." (PMID 34580349, 2021).
tumor (continued). "Later, whole‐genome sequencing of four RB tumors and their paired germline DNA samples has revealed that RB genomes are more stable than previously thought and very few genetic lesions are required for tumor progression after RB1 inactivation." (PMID 32840881, 2021). "Gene expression analysis of MSL tumours showed that they retained RB1 while displaying significantly lower CDK4 and CDK6 expression levels, which means they have a pre-set level for reduced cell cycle progression." (PMID 34316709, 2021). "Like adenovirus E1A and polyomavirus large tumor antigens, LXCXE motif-containing HPV E7 proteins bind RB1 and abrogate the formation of RB1/E2F repressor complexes, thereby causing aberrant S-phase entry." (PMID 34465025, 2021). "Here we identified two tumours which were biallelically null for RB1 that also harboured focal MYCN amplifications, in the case of PD34256 an amplification of 168-fold, while PD37495 was amplified 51-fold." (PMID 33670346, 2021). "RB1, a tumor‐suppressor gene and negative regulator of cell cycle, regulates phosphoprotein in the nucleus through PB1‐encoded protein that contains n‐terminal, A/B pocket, and c‐terminal domains." (PMID 32508051, 2020). "We identified that miR-181a’s tumor forming ability was mediated through the cooperative inhibition of the classic tumor suppressor RB1 and STING." (PMID 32591511, 2020). "Though RB1 inhibition phenocopied the tumor initiating phenotypes observed in miR-181a overexpressing FTSECs, the nuclear defects and DNA damage phenotypes observed in the pshRB1 cells were consistently more diminished compared to the pmiR-181a cells." (PMID 32591511, 2020). "We also included genes with well-established roles in cancer, including MYC (proto-oncogene), RB1 (tumor suppressor), and EIF4E (translation initiation factor), to contrast with the aaRS genes." (PMID 33266490, 2020). "The RB1 gene is a tumor suppressor, located in 13q14, that codes for a protein that is a negative regulator of the cell cycle." (PMID 33294214, 2020).
tumor (continued). "Inactivation of RB1 expression in tumor cells leads to the deregulation of activity of transcription factors E2F1, E2F2, and E2F3, which control the expression of genes involved in differentiation, development, proliferation, and apoptosis." (PMID 32429447, 2020). "In these cases, two random somatic hits must occur in the RB1 gene of a single retinal cell to allow for the tumor to arise." (PMID 32633890, 2020). "The role of RB1 as a tumor suppressor in the early stages of HGSOC oncogenic transformation is well established." (PMID 32591511, 2020). "RB1 was the first molecularly defined tumor suppressor by suppressing cell cycle progression and controlling chromatin remodeling and cell death." (PMID 32819446, 2020). "RB1 was identified by positional cloning and after subsequent molecular analysis, it became known as the first tumor suppressor gene, giving robust evidence for the genetic predisposition of cancer development in some cases." (PMID 32664691, 2020). "Across a large cell panel, the activity profiles of abemaciclib and palbociclib were closely related (p < 0.001), and RB1 depletion conferred resistance to abemaciclib, suggesting that the predominant anti-tumor activity is driven by CDK4/6 inhibition." (PMID 32391118, 2020). "The level of Rb1 is known to be inversely correlated to p16 (CDKN2A) level, and alterations in the Rb1/p16 tumor suppressor checkpoint pathway are associated with MIBC and increased risk of progression." (PMID 32784716, 2020). "We also observed the same result in mice tumor tissues where α-tubulin level was overall reduced in RB1−/− tumors, and was further reduced by the AURKA inhibitor treatment or AURKA silencing." (PMID 33037191, 2020). "The canonical role of RB1 as a tumor suppressor is through inhibition of the G1/S cell cycle progression." (PMID 32591511, 2020). "Taken together, these data indicated that RB1 knockdown in the FTSECs was able to phenocopy miR-181a’s effects on cellular viability, anchorage independent growth, cellular survival, and tumor formation." (PMID 32591511, 2020). "As the first identified tumor suppressor gene, the retinoblastoma gene RB1 has been proved to regulate the various biologic processes, including cell cycle progression, terminal differentiation and DNA replication." (PMID 32694239, 2020). "This translates to a significant increase of ~16 weeks in the mean survival of tumor-bearing mice from 33.8 weeks for Rb1/p107 DKO to 49.6 weeks for Rb1/p107/Hells TKO (p = 0.0052)." (PMID 32071286, 2020).
tumor (continued). "Double heterozygous Men1 and Rb1 knockout mice have been reported to develop the same tumor spectrum as the respective single knockout mice." (PMID 32733644, 2020). "In agreement with our data, RB1 mutations occurs in 35% of LCNECs as well as typical NSCLC mutations such as KEAP1 and STK11 only occur in this tumor variants compared to both NETs and SCLCs (p < 0.0001)." (PMID 32987854, 2020). "Given that CDKN2A is a crucial component of the RB1 pathway, perturbations in the tumor suppressor pathway will result with deletion of CDKN2A." (PMID 31906059, 2019). "Among mutations specific to the m-PET-high tumor were a gain of function mutation of PIK3CA (T1258C) and a truncating mutation of RB1 (splice site, chromosome 13: 49047536 del)." (PMID 30760837, 2019). "In the remaining patient, while we were able to detect the two large RB1 exonic deletions present in the tumour, the start point of each deletion was discordant between the two sample types." (PMID 30745306, 2019). "Taken together, these findings suggest that the high levels of proliferation seen in basal-like tumours are unlikely driven by traditional CCND1/RB1 signalling." (PMID 30819233, 2019). "CDC25 oncogenic properties have been illustrated by cellulartransformation, aneuploidy, and tumor formation in vivo, eitherin cooperation with oncogenic RAS or RB1 loss." (PMID 31930281, 2019). "The retinoblastoma family or pocket proteins is a family of tumour suppressors that consist of the three members pRb (RB1), p107, and p130 (RB2)." (PMID 31408949, 2019). "The results showed that in many cases, chemoresistant tumours inactivated tumour suppressor genes (RB1, NF1, RAD51 paralog B (RAD51B), PTEN) through gene breakage." (PMID 31146417, 2019). "This analysis yielded a spectrum of somatic genetic alterations putatively driving tumor evolution, including gene-fusions and chromosomal amplifications and deletions (including recurrent amplification of Met and Myc and deletion of Rb1)." (PMID 30674894, 2019). "Specifically, HMGA1 enhances E2F transcriptional activity by directly binding RB1, inhibiting its tumor suppressive activity." (PMID 31311575, 2019). "We found that the phosphorylation of Rb1 was significantly elevated in tumor tissue, but rarely detected in normal pancreatic tissue." (PMID 30910991, 2019).
tumor (continued). "RB1’s protein product, pRB, inhibits E2F transcription factors by binding and inactivating them, and its absence enables miR-17∼92–driven tumor formation." (PMID 31616462, 2019). "While RB1 is a well-established tumor suppressor, FOXO family of transcription factors are associated with diverse functions such as cell cycle regulation, differentiation, apoptosis, DNA repair and reactive oxygen species (ROS) detoxification." (PMID 28887603, 2018). "The Rb1/PPD NPs groups showed better therapeutic effect (71.3% of tumor growth inhibition at day 20) and higher survival rate (33.3% survival at day 30)." (PMID 29473838, 2018). "Comparison of rb1 tumor and rb1/rb1 germline mutant larval transcriptomes shows that the altered oligoneural precursor signature is specific to tumor tissue." (PMID 29914980, 2018). "Retinoblastoma binding protein 5 (RBBP5) was determined as the binding protein of RB transcriptional corepressor 1 (RB1) which is one of the best studied tumor suppressor proteins." (PMID 30533424, 2018). "Tumor progression was associated with an imbalance in the acetylation and deacetylation of histones and increasing the HDAC levels potentially repressed the tumor suppression genes RB1 and CDKN2A, initiating tumor formation." (PMID 29301348, 2018). "Transcriptome and molecular analysis of zebrafish rb1 tumors indicated that an oligoneural precursor phenotype drives tumor proliferation." (PMID 29914980, 2018). "Compared to free PPD, Rb1/PPD NPs showed a high level of PPD accumulation in the tumor tissues and low levels of PPD accumulation in the liver, spleen, lung, and kidney." (PMID 29473838, 2018). "The high-risk HPV E7 proteins cause S-phase competence in differentiating cells by targeting the retinoblastoma tumor suppressor, RB1, for degradation." (PMID 29568286, 2018). "RB1 is part of the RB1 tumor suppressing pathway, which is commonly inactivated in many cancers, including HCC." (PMID 29416609, 2018). "Differential gene expression showed that >36% of all transcriptional regulators, including >170 chromatin remodelers, are altered in the rb1 tumor transcriptome, which suggests epigenetic control of gene expression drives tumorigenesis." (PMID 29914980, 2018). "In the network module and gene set enrichment analysis, the RB tumor suppressor-related pathway and DNA damage repair system related pathways such as DNA replication and homologous recombination was enriched in the RB1 del group." (PMID 30598078, 2018).